NR0B2 (nuclear receptor subfamily 0 group B member 2)
Diseases named in the same sentence as NR0B2 in open-access papers (continued):
Sharing a sentence is not in itself a finding about the gene and the disease.
colon cancer (4 papers, 2012 to 2021). "Conversely, higher NR0B2 expression is a worse prognosis factor in colon cancers and B-cell lymphomas." (PMID 34055653, 2021). "However, higher NR0B2 expression is a worse survival factor in colon cancers and B-cell lymphomas." (PMID 34055653, 2021).
hyperlipidemia (4 papers, 2015 to 2026). "In addition, fenofibrate, a drug clinically used for hyperlipidemia, was found to attenuate experimental sepsis through NR0B2 upregulation." (PMID 29056901, 2017).
Hepatitis (3 papers, 2018 to 2026). Inflammation of the liver. "In our previous study, hepatocyte-specific deficiency of small heterodimer partner (SHP; NR0B2), which belongs to the same NR0B family as DAX1, was much more susceptible to the ConA model of hepatitis by modulating neutrophil migration in a mainly C-X-C motif ligand 2 (CXCL2)-dependent manner." (PMID 36430486, 2022).
lipodystrophy (3 papers, 2007 to 2021). A congenital or acquired disorder characterized by abnormal loss or redistribution of the adipose tissue in the body. "Three lipodystrophy-associated genes, Histone deacetylase 3 (HDAC3), Nuclear receptor subfamily 0 group B member 2 (NR0B2), and small ubiquitin-like modifier 1 (SUMO1) were also present in this network." (PMID 34017037, 2021).
renal carcinoma (3 papers, 2021 to 2024). A carcinoma arising from the epithelium of the renal parenchyma or the renal pelvis. "They speculated that NR0B2 triggers G2 arrest in renal cancer cells, preventing them from entering mitosis." (PMID 39336801, 2024).
bladder cancer (2 papers, 2021 to 2022). "In addition, NR0B2 is a favorite survival factor in bladder cancers but a worse factor in thyroid cancers, lung squamous cancers, uterine corpus endometrial cancers, and head-neck squamous cancers." (PMID 34055653, 2021). "Survival data showed that NR0B2 expression is a favorite prognosis factor in patients with liver, kidney, lung, urinary bladder cancers but is a negative factor in patients with colon, thyroid, uterine, and head-neck cancers." (PMID 34055653, 2021).
colorectal adenocarcinoma (2 papers, 2016 to 2021). The most common type of colorectal carcinoma. "Meanwhile, lung adenocarcinomas exerted a downregulation, but colorectal adenocarcinomas upregulated NR0B2 expression." (PMID 34055653, 2021). "Meanwhile, about ten datasets showed a significant increase of NR0B2 gene expression in human cancers, such as the esophagus and colorectal adenocarcinoma, ovarian serous surface papillary carcinoma, and brain medulloblastoma." (PMID 34055653, 2021).
lung carcinoma (2 papers, 2017 to 2021). "We found a similar expression pattern, NR0B2 gene downregulation in liver, kidney, and lung carcinomas but upregulation in the colon and rectal adenocarcinomas." (PMID 34055653, 2021).
Parkinson disease (2 papers, 2021). A progressive degenerative disorder of the central nervous system characterized by loss of dopamine producing neurons in the substantia nigra and the presence of Lewy bodies in the substantia nigra and locus coeruleus. "How are NEUROD1 and NR0B1 and NR0B2 impacted in Parkinson’s disease?" (PMID 34941945, 2021).
viral hepatitis (2 papers, 2021 to 2024). An acute or chronic inflammation of the liver parenchyma caused by viruses. "Interestingly, higher NR0B2 expression is a favorite factor for overall survival in patients with viral hepatitis history, especially for those without alcohol consumption and Asian male patients." (PMID 34055653, 2021).
B-cell lymphomas (1 paper, 2021). "In agreement with a significant upregulation of NR0B2 gene expression in colon and B-cell lymphoma, higher NR0B2 expression levels were significantly associated with worse overall survival in these patients." (PMID 34055653, 2021). "NR0B2 expression is a favorite factor in human cancers from the liver, kidney, lung, urinary bladder, breast, eye, and soft fat tissues, but is a worse factor in colon, thyroid, uterine, and head-neck cancers, as well as B-cell lymphoma." (PMID 34055653, 2021). "NR0B2 gene expression significantly correlated with patient overall survival status in multiple human malignancies, including lung, kidney, breast, urinary bladder, thyroid, colon, and head-neck cancers, as well as liposarcoma and B-cell lymphoma." (PMID 34055653, 2021).
breast tumors (1 paper, 2024). "In breast tumors, NR0B2 expression is negatively correlated with FOXP3, a marker for Tregs, suggesting that NR0B2 may reduce immunosuppression in the tumor microenvironment." (PMID 39336801, 2024).
celiac disease (1 paper, 2022). An autoimmune genetic disorder with an unknown pattern of inheritance that primarily affects the digestive tract. "Moreover, nutritional intervention of resveratrol could affect the differential expression of Aire, Ubd, Fgf15 and Nr0b2 genes in the intestine of the mice with celiac disease." (PMID 35450077, 2022).
dilated cardiomyopathy (1 paper, 2021). Cardiomyopathy which is characterized by dilation and contractile dysfunction of the left and right ventricles. "LPIN1, PPP1R3C, PTPN1, CREM, and NR0B2 were identified as the main effectors in metabolism dysregulation in the remote zone and were found differentially expressed also in the myocardium of patients with ischemic and/or dilated cardiomyopathy." (PMID 34722683, 2021).
eye cancers (1 paper, 2021). "Survival analysis showed that higher NR0B2 expression levels were associated with better survival status in liver, lung, breast, soft tissue (liposarcoma), and eye cancers." (PMID 34055653, 2021).
gastric diseases (1 paper, 2024). "In order to determine the causal relationship of NR0B2 in gastric diseases, we conducted a drug-target Mendelian randomization analysis." (PMID 39336801, 2024). "To explore the correlation and causation between NR0B2 expression and gastric diseases, we plan to combine a GEO database analysis with drug-target Mendelian randomization." (PMID 39336801, 2024). "Therefore, we used MR to explore the causal relationship between NR0B2 expression and gastric diseases." (PMID 39336801, 2024). "To establish causality between NR0B2 expression and gastric diseases, we conducted an MR analysis." (PMID 39336801, 2024). "Examining the correlation between the expression of NR0B2 and the risk of gastric diseases could open a new path for treatment and drug development." (PMID 39336801, 2024). "The Gene Expression Omnibus (GEO) database was utilized to explore NR0B2 gene expression profiles in gastric diseases." (PMID 39336801, 2024). "Our study aims to analyze and explore the effect of NR0B2 expression on gastric diseases using bioinformatics methods and drug-target Mendelian randomization methods." (PMID 39336801, 2024). "Remarkably, there are only a few reports on the role of NR0B2 in gastric diseases." (PMID 39336801, 2024).
gastric ulcer (1 paper, 2024). An ulcerated lesion in the mucosal surface of the stomach. "A similar relationship between the expression of NR0B2 and gastric ulcers was found in the ukb-d-K25 dataset (p = 0.032; OR = 0.991) and the ebi-a-GCST90018851 dataset (p = 0.006)." (PMID 39336801, 2024).
gastritis (1 paper, 2024). Inflammation of the stomach. "An intriguing finding of the present study is that elevated NR0B2 is a risk factor for gastritis." (PMID 39336801, 2024). "In contrast, a high NR0B2 level increases the risk of gastritis." (PMID 39336801, 2024). "The long-term high expression of NR0B2 may affect the concentration of triglycerides, thereby causing lipid metabolism disorders, increasing the risk of gastritis." (PMID 39336801, 2024). "In gastritis, the co-expressed genes NR1I3, NR6A1, and NR0B2 are associated with anti-inflammatory steroid hormone synthesis and metabolism." (PMID 39336801, 2024). "Interestingly, in gastritis, NR0B2 expression significantly correlates with M2 macrophage infiltration." (PMID 39336801, 2024).
intestinal cancer (1 paper, 2021). "NR0B2 expression is mostly downregulated in most common cancers but also upregulated in a few intestinal cancers." (PMID 34055653, 2021).
liposarcoma (1 paper, 2021). A usually painless malignant tumor that arises from adipose tissue. "Interestingly, higher NR0B2 expression levels were also a favorite prognostic factor in liposarcoma and eye uveal melanoma patients." (PMID 34055653, 2021).
tumor (38 papers, 2007 to 2024). "Among those, the loss of distal chromosome 4q, including the tumor suppressors Runx3 and Nr0b2/Shp, was an early and persistent event during DEN/PB-induced hepatocarcinogenesis." (PMID 34771745, 2021). "NR0B2 expression in both normal and tumor tissues of the kidney, liver, and stomach is higher than that in other organs." (PMID 39336801, 2024). "We, therefore, analyzed the correlation between NR0B2 expression and tumor-infiltrating lymphocytes using the TIMER database." (PMID 34055653, 2021). "Our analysis discovered a partial but significant correlation between lower NR0B2 expression levels and higher tumor infiltration of B cells, CD8+ T cells, and dendritic cells." (PMID 34055653, 2021). "Interestingly, while high CYP11A1 and HSD11B1 expression resulted in poor survival, suggesting that tumours efficiently suppressing the immune system via glucocorticoids have a growth advantage, high NR0B2 was beneficial for survival, likely due to increased suppression of LRH‐1." (PMID 36861295, 2023). "Because inflammatory response and tumor-infiltrating lymphocytes have diverse functions in tumor progression and anti-tumor immunity, the clinical significance of this negative correlation between NR0B2 expression and tumor-infiltrating lymphocytes needs more investigation." (PMID 34055653, 2021).
cancer (18 papers, 2011 to 2025). A tumor composed of atypical neoplastic, often pleomorphic cells that invade other tissues. "Our analysis aligns with previous findings, demonstrating that NR0B2 expression is reduced in various cancers compared to normal tissue." (PMID 39336801, 2024). "In conclusion, in this study, we discovered that NR0B2 expression is predominantly downregulated in multiple malignant tissues and upregulated in few cancers." (PMID 34055653, 2021). "In this study, we sought to investigate if NR0B2 gene expression is altered crossing the spectrum of human cancers." (PMID 34055653, 2021). "Our study revealed that NR0B2 gene expression is mainly downregulated in many common cancers, while its upregulation is only seen in fewer cancer types." (PMID 34055653, 2021). "The role of NR0B2 gene has been explored in several cancers." (PMID 39336801, 2024). "In addition, there are only very few reports related to the involvement of cellular signaling pathways in the regulation of NR0B2 gene expression in cancer cells." (PMID 34055653, 2021). "We then compared NR0B2 gene expression in cancer tissues with their matched benign counterparts." (PMID 34055653, 2021). "However, it is not clear if NR0B2 expression is associated with cancer survival or disease progression and how NR0B2 gene expression is regulated at the molecular level." (PMID 34055653, 2021). "However, it is not clear if NR0B2 expression is also altered in other human cancer types and if the alteration is associated with patient disease history or outcome." (PMID 34055653, 2021). "Small Heterodimer Partner (SHP; NR0B2) is an orphan receptor that acts as a transcriptional regulator, controlling various metabolic processes, and is a potential therapeutic target for cancer." (PMID 39336801, 2024). "Currently, NR0B2 gene regulation is not fully clear, especially in human cancers." (PMID 34055653, 2021).
infection (5 papers, 2015 to 2025). The state of being infected such as from the introduction of a foreign agent such as serum, vaccine, antigenic substance or organism. "Knockdown of the atypical orphan nuclear receptor NR0B2 (alias SHP), in contrast to one previous report, significantly decreased HCV replication in our hands, both, upon infection in Huh7-Lunet cells, as well as in the Huh7-LucUbiNeo stable replicon cell line." (PMID 31905685, 2019).
NR0B2 also shares sentences with these, for which no sentence is quoted: steatosis (16 papers); Insulin resistance (12); metabolic disease (8); dyslipidemia (7); liver disease (7); Hypercholesterolemia (6); intrahepatic cholestasis (5); atherosclerosis (4); Cirrhosis (4); metabolic dysfunction-associated steatohepatitis (4); Sepsis (4); type 2 diabetes (4); colitis (3); fibrosis (3); viral infection (3); adenovirus infection (2); adrenal hypoplasia congenita (2); cardiac hypertrophy (2); cervical cancer (2); Cholestatic liver disease (2); non-alcoholic fatty liver (2); non-alcoholic fatty liver disease (2); prostate carcinoma (2); acute kidney injury (1); adenoma (1); adrenal cancer (1); adrenocortical tumor (1); age (1); alcohol abuse (1); alcoholic liver diseases (1).
A further 58 diseases each share a sentence with NR0B2 in 1 paper.